GALNT13 (polypeptide N-acetylgalactosaminyltransferase 13)
Description:
Catalyzes the initial reaction in O-linked oligosaccharide biosynthesis, the transfer of an N-acetyl-D-galactosamine (GalNAc) residue from UDP-GalNAc to a serine or threonine residue on the protein receptor. Generates GalNAc-O-Ser/Thr structure also known as Tn antigen, which itself is immunogenic but also serves as a precursor for the synthesis of different mucin-type O-glycan core structures. Contributes to the synthesis of O-linked glycans on mucins and proteoglycans of the central nervous system. May promote neurogenesis through glycosylation and stabilization of PDPN (By similarity). [Isoform 1]: Can glycosylate both unmodified peptides and glycopeptides that already contain an O-linked GalNAc sugar. Transfers GalNAc to Thr-/Ser-rich tandem repeats GTTPSPVPTTSTTSAP of MUC5AC, specifically on Thr-3 of non-glycosylated MUC5AC peptide, on Thr-12 and Thr-13 of preglycosylated MUC5AC at Thr-3 (MUC5AC-3), on Thr-3 of preglycosylated MUC5AC at Thr-13 (MUC5AC-13) and on Thr-12 of preglycosylated MUC5AC at Thr-3 and Thr-13 (MUC5AC-3,13). Transfers GalNAc to three consecutive serine/threonine residues on SDC3 forming a triplet-Tn epitope expressed in Purkinje cells of the developing brain. [Isoform 4]: Can glycosylate both unmodified peptides and glycopeptides that already contain an O-linked GalNAc sugar. Transfers GalNAc to Thr-/Ser-rich tandem repeats GTTPSPVPTTSTTSAP of MUC5AC, specifically on Thr-3 of non-glycosylated MUC5AC peptide, on Thr-12 and Thr-13 of preglycosylated MUC5AC at Thr-3 (MUC5AC-3), on Thr-3 of preglycosylated MUC5AC at Thr-13 (MUC5AC-13) and on Thr-12 of preglycosylated MUC5AC at Thr-3 and Thr-13 (MUC5AC-3,13).
Synonyms: GalNAc-T13; KIAA1918
Tractability: Antibody: UniProt predicts a signal peptide or a membrane-spanning region.
Target class: Enzyme; Transferase
Gene: Protein-coding gene on chromosome 2 (153,871,398 to 154,456,630, forward strand). Ensembl gene ENSG00000144278.
Subcellular location: Golgi apparatus membrane
Pathways (Reactome):
Metabolism of proteins: O-linked glycosylation of mucins
Gene Ontology:
Molecular function: polypeptide N-acetylgalactosaminyltransferase activity
Biological process: protein O-linked glycosylation via N-acetyl-galactosamine; protein O-linked glycosylation
Cellular component: Golgi apparatus; Golgi membrane
Genetic constraint (gnomAD): Loss-of-function variants: 14 observed, 29.76 expected, observed/expected ratio (o/e) 0.47, 90% interval 0.31 to 0.74. The upper end of that interval is the gene's LOEUF score, 0.74, which puts it in group 3 of 6, group 1 being the genes least tolerant of losing a copy. Missense variants: 310 observed, 359.97 expected, observed/expected ratio (o/e) 0.86, 90% interval 0.78 to 0.95. Synonymous variants: 124 observed, 127.31 expected, observed/expected ratio (o/e) 0.97, 90% interval 0.84 to 1.13.
Homologues: Orthologues: mouse Galnt13 (99% identical), macaque GALNT13 (95% identical), rabbit GALNT13 (95% identical), pig GALNT13 (94% identical), chimpanzee GALNT13 (94% identical), rat Galnt13 (94% identical), dog GALNT13 (94% identical), guinea pig GALNT13 (91% identical), zebrafish galnt13 (88% identical), tropical clawed frog galnt13 (88% identical), Drosophila melanogaster Pgant5 (63% identical), Caenorhabditis elegans gly-3 (51% identical), and 11 more. Paralogues in human: GALNT1 (85% identical), GALNT6 (45% identical), GALNT10 (43% identical), GALNT3 (42% identical), GALNTL6 (42% identical), GALNT4 (42% identical), GALNT2 (41% identical), GALNT12 (41% identical), GALNT11 (40% identical), GALNT14 (38% identical), GALNT7 (37% identical), GALNT5 (37% identical), and 7 more.
Diseases named in the same sentence as GALNT13 in open-access papers:
GALNT13 is named in the same sentence as 24 diseases in open-access papers, as found by Europe PMC text mining. Sharing a sentence is not in itself a finding about the gene and the disease. The quoted sentences say what the papers report.
neuroblastoma (6 papers, 2014 to 2024). Neuroblastoma (NB) is the most common solid, extracranial childhood tumor. "Thus, GALNT6 and GALNT13 display elevated levels in different cancer types, including breast and gastric carcinomas (GALNT6) and lung cancer and neuroblastoma (GALNT13), as both genes are found to be associated with tumor invasion and metastasis." (PMID 24504219, 2014). "Another study showed that GALNT13 or its product ppGalNAcT13 is abnormally expressed in prostate cancer, lung cancer, and neuroblastoma and is related to the prognosis of patients." (PMID 36575396, 2022). "Furthermore, a study demonstrated a strong correlation between GALNT13 expression and poor clinical outcomes at diagnosis in human neuroblastoma." (PMID 38584840, 2024). "A previous study reported that the expression of GALNT13 mRNA was the highest in brain tissues, and it may be a strong predictor of poor clinical outcome in neuroblastoma patients." (PMID 33168785, 2020). "As the bone marrow (BM) is the preferential site for NB dissemination, BM molecular analysis of human neuroblastoma patients has shown high expression of GALNT13, which was identified as a new indicator for disseminated neuroblasts in BM of NB patients." (PMID 27322213, 2016). "GALNT13, like GALNT1, is highly expressed in all neuroblastoma (NB) cells, but not in glioblastoma cells." (PMID 27322213, 2016).
glioma (5 papers, 2008 to 2024). A benign or malignant brain and spinal cord tumor that arises from glial cells (astrocytes, oligodendrocytes, ependymal cells). "The known glioma risk variant rs55705857 in CCDC26 was co-inherited together with rare variants in GALNT13, MYO10 or AR in three out of six families carrying these rare variants, and it was also detected in affected cases in three additional families." (PMID 38773237, 2024). "This confirmed that gliomas with 1p19q codeletion overexpressed neuronal/normal brain genes (AKR1C3, C20orf42, CTTNBP2, L1CAM, GALNT13) as well as genes implicated in gliogenesis and neurogenesis (OLIG2, BMP2, NOG, DCX, ATOH8)." (PMID 18492260, 2008). "GALNT13 exhibits particularly high expression in neuronal cells and may play an important role in glioma development." (PMID 38584840, 2024). "When considering the rate, inheritance pattern, and population frequencies of detected rare, damaging coding variants in MYO10, AR and GALNT13, enhancer-linked risk variant in CCDC26, and other detected risk variants, our results suggest polygenic inheritance of familial glioma in Finland." (PMID 38773237, 2024). "In gliomas, GALNT13 is overexpressed in LGGs based on database analysis." (PMID 38773237, 2024). "Similar to the TCGA datasets, all 11 genes exhibited WHO grade-dependent expression in glioma samples, with 6 upregulated (LDHA, MIF, NAMPT, PGK1, SAT1, and PLOD2) and 5 downregulated genes (ALDOC, ABAT, ADCY2, GALNT13, and PDE8B)." (PMID 38989284, 2024). "Consistent with the changes in expression, patients with higher expression of LDHA, MIF, NAMPT, PGK1, SAT1, and PLOD2, and lower expression of ALDOC, ABAT, ADCY2, GALNT13, and PDE8B showed poorer survival rates in all glioma samples." (PMID 38989284, 2024).
lung carcinoma (5 papers, 2014 to 2024). "According to studies, GALNT13 is highly expressed in lung cancer and is linked to a bad patient prognosis." (PMID 38396140, 2024). "The GALNT13 protein is a member of the GalNAcT protein family, and it is suggested that it can be a potential prognostic factor in lung cancer." (PMID 38732015, 2024). "Moreover, all of the eight novel hypermethylation driver genes (PCDH17, IRX1, ITGA5, HSPB6, TBX5, ADCY8, GALNT13 and TCTEX1D1) were successfully validated in an independent cohort via a pyrosequencing approach, with an AUC of 0.965 for prediction of lung cancer patients." (PMID 33859751, 2021). "The remaining eight genes are newly identified methylation drivers in lung cancer, including 5 known cancer methylation driver genes in other cancer types (HSPB6, IRX1, ITGA5, PCDH17, TBX5) and 3 novel genes that had not been previously reported (ADCY8, GALNT13 and TCTEX1D1)." (PMID 33859751, 2021).
prostate carcinoma (3 papers, 2019 to 2022). A carcinoma that arises from epithelial cells of the prostate gland. "Furthermore, authors revealed such genes for the TMPRSS2-ERG prostate cancer molecular subtype (B4GALNT4, ASRGL1, MYBPC1, RGS11, SLC6A14, GALNT13 and ST6GALNAC1)." (PMID 36077746, 2022). "Additionally, we revealed such genes for the TMPRSS2-ERG prostate cancer molecular subtype (B4GALNT4, ASRGL1, MYBPC1, RGS11, SLC6A14, GALNT13, and ST6GALNAC1)." (PMID 31447885, 2019).
pulmonary hypertension (2 papers, 2018 to 2023). Increased pressure within the pulmonary circulation due to lung or heart disorder. "Interestingly, GALNT13 has been previously identified as a risk gene relevant to sickle cell disease-associated pulmonary hypertension, which may play roles in endothelial permeability." (PMID 36944699, 2023).
astrocytomas (1 paper, 2024). "In the TCGA diffuse glioma cohort, one GBM tumor harbored homozygous deletion of GALNT13 and six IDH-mutant astrocytomas amplification in AR15,17,18." (PMID 38773237, 2024).
autism (1 paper, 2013). Persistent deficits in social interaction and communication and interaction as well as a markedly restricted repertoire of activity and interest as well as repetitive patterns of behavior. "The top-ranked clique in our analysis (hereafter will be referred as Clique I), was delineated by the autism genes: Ptchd1, Galnt13, Dpp6 and Astn2, and included another 29 genes, inter-connected with a co-expression values of ≥70%." (PMID 23935468, 2013).
behavioral disorders (1 paper, 2021). "A case of a 13-year-old girl showed a relationship of GALNT13 with minor facial and digital anomalies, mild developmental delay during infancy and behavioral disorders, which might reflect high expression of GALNT13 in the brain." (PMID 34576978, 2021).
breast carcinoma (1 paper, 2022). "With respect to the O-GalNAc pathway, we observed alterations in several related glycogenes including the downregulation of GCNT4, GALNT13, GALNT16 and C1GALT1, and upregulation of ST3GAL1, ST6GALNAC4 and GAL3ST2 in Her2+ breast cancer tissue." (PMID 36282863, 2022).
diffuse astrocytoma (1 paper, 2024). A low-grade (WHO grade II) astrocytic neoplasm. "GALNT13 variant c.553C>T (R185C) was detected in Family A in two affected siblings: one suffering from pilocytic astrocytoma (PA) (II-1) and the other from diffuse astrocytoma grade II (II-2)." (PMID 38773237, 2024).
lung disease (1 paper, 2020). "However, the role of GALNT13 is unknown in terms of lung disease." (PMID 33168785, 2020).
ovarian carcinoma (1 paper, 2022). A malignant neoplasm originating from the surface ovarian epithelium. "Particularly, siRNA-mediated knockdown of seven genes, CASC10, ATP11B, EMP1, GAS1, SLC6A15, GALNT13, and PDLIM3, significantly reduced cell proliferation of ovarian cancer cells." (PMID 35887085, 2022).
schizophrenia (1 paper, 2020). A major psychotic disorder characterized by abnormalities in the perception or expression of reality. "However, confirmation of GALNT13 as a schizophrenia risk locus will require detailed follow-up and replication in an independent Latino cohort." (PMID 31591465, 2020). "While GWAS of schizophrenia in admixed African ancestry individuals did not yield any genome-wide significant findings, our analysis of Latino cases and controls revealed a novel genome-wide association with SNPs in GALNT13 at 2q23.3." (PMID 31591465, 2020).
cancer (4 papers, 2014 to 2024). A tumor composed of atypical neoplastic, often pleomorphic cells that invade other tissues. "Understanding the mechanism of GalNAc-T13 glycosylation is likewise critical because GALNT13 is associated with many cancers, further highlighting the importance of this study." (PMID 38416819, 2024).
CNS tumors (1 paper, 2023). "Considering that GALNT13 is basically expressed in the fetal brain, both GALNT13 and its products of translation trimeric Tn may play an essential role in cell growth and proliferation and serve as a specific maker for malignant CNS tumors." (PMID 38293671, 2023).
GALNT13 also shares sentences with these, for which no sentence is quoted: tumor (3 papers); Ataxia (1); cervical cancer (1); developmental delay (1); gastric carcinoma (1); ischemic stroke (1); oligodendroglioma (1); pilocytic astrocytoma (1); sickle cell disease (1).